SP6 (Sp6 transcription factor)
Description:
Promotes cell proliferation (By similarity). Plays a role in tooth germ growth (By similarity). Plays a role in the control of enamel mineralization. Binds the AMBN promoter.
Synonyms: KLF14; Epfn; AI1K; EPIPROFIN
Tractability: No criterion of Open Targets' tractability assessment is met for any kind of drug.
Gene: Protein-coding gene on chromosome 17 (47,844,908 to 47,855,874, reverse strand). Ensembl gene ENSG00000189120.
Subcellular location: Nucleus
Subcellular location (Human Protein Atlas): Nucleoplasm; Centrosome; Mitotic spindle
Gene Ontology:
Molecular function: protein binding; DNA-binding transcription factor activity, RNA polymerase II-specific; RNA polymerase II cis-regulatory region sequence-specific DNA binding
Biological process: regulation of transcription by RNA polymerase II; epithelial to mesenchymal transition; odontogenesis
Cellular component: nucleoplasm; chromatin; nucleus; cytosol
Genetic constraint (gnomAD): Loss-of-function variants: 12 observed, 22.27 expected, observed/expected ratio (o/e) 0.54, 90% interval 0.34 to 0.87. The upper end of that interval is the gene's LOEUF score, 0.87, which puts it in group 3 of 6, group 1 being the genes least tolerant of losing a copy. Missense variants: 482 observed, 503.06 expected, observed/expected ratio (o/e) 0.96, 90% interval 0.89 to 1.03. Synonymous variants: 238 observed, 233.91 expected, observed/expected ratio (o/e) 1.02, 90% interval 0.92 to 1.13.
Homologues: Orthologues: chimpanzee SP6 (100% identical), dog SP6 (98% identical), macaque SP6 (98% identical), pig SP6 (97% identical), mouse Sp6 (96% identical), rat Sp6 (96% identical), guinea pig SP6 (95% identical), rabbit SP6 (78% identical), tropical clawed frog sp6 (48% identical), zebrafish sp6 (34% identical), Drosophila melanogaster luna (16% identical). Paralogues in human: SP8 (45% identical), SP9 (38% identical), SP7 (35% identical), SP5 (31% identical), KLF11 (22% identical), KLF10 (21% identical), KLF4 (19% identical), KLF1 (19% identical), KLF14 (18% identical), KLF2 (18% identical), KLF13 (17% identical), KLF5 (17% identical), and 10 more.
Diseases named in the same sentence as SP6 in open-access papers:
SP6 is named in the same sentence as 50 diseases in open-access papers, as found by Europe PMC text mining. Sharing a sentence is not in itself a finding about the gene and the disease. The quoted sentences say what the papers report.
amelogenesis imperfecta (3 papers, 2020). Amelogenesis imperfecta (AI) represents a group of developmental conditions affecting the structure and clinical appearance of the enamel of all or nearly all the teeth in a more or less equal manner, and which may be associated with morphologic or biochemical changes elsewhere in the body. "Msx2 and Sp6 mouse mutants, exhibit similar amelogenesis defects, namely enamel hypoplasia, while humans with amelogenesis imperfecta (AI) carry mutations in the human homologues of MSX2 or SP6 genes." (PMID 33192593, 2020). "A missense variant in Epfn/Sp6 is associated with amelogenesis imperfecta in humans." (PMID 33255698, 2020).
depression (3 papers, 2014 to 2025). "Thus, acupuncture stimulation of SP6 is capable of attenuating complex behaviors associated with depression and anxiety via the modulation of the central noradrenergic system." (PMID 24527041, 2014). "Therefore, in clinical practice, in addition to the conventional matching points of GV20 and GC29, the combination of SP6 may have a better therapeutic effect on the alleviation of depression." (PMID 41244868, 2025). "The combination of SP6, LR3, and BL18 leads to significant alleviation of symptoms of depression by dispersing liver qi and relieving qi stagnation that is considered to be the leading TCM pathogenesis of PSD according to TCM theory." (PMID 29499745, 2018). "This indicates that acupuncture stimulation of SP6 might be effective in preventing patients with drug addiction from relapsing into drug seeking while trying to quit, by relieving some of the discomfort of morphine withdrawal symptoms including depression and anxiety." (PMID 24527041, 2014).
Anxiety (2 papers, 2014 to 2023). Intense feelings of nervousness, tension, or panic often arise in response to interpersonal stresses. "SP6 is one of the most common points used in treating psychological dysfunctions, and recent studies have reported the anti-anxiety and antidepressant-like effects of SP6." (PMID 37893778, 2023).
Cerebral ischemia (2 papers, 2022 to 2024). Restriction of arterial blood supply to the brain associated with insufficient oxygenation to support the metabolic requirements of the tissue. "In conclusion, EA at points “LU5,” “LI4,” “ST36,” and “SP6” can significantly improve the symptoms of nerve injury and morphological changes of brain cells in mice with cerebral ischemia/reperfusion injury, reduce the infarct area, and protect brain tissue from ischemic injury." (PMID 35600074, 2022). "Electroacupuncture stimulation of SP6 inhibits the p38 MAPK pathway, thereby attenuating apoptotic index in hippocampal cells of cerebral ischemia/reperfusion-injured rats." (PMID 39363248, 2024).
enamel hypoplasia (2 papers, 2020 to 2022). "Both, Msx2 and Sp6 mouse mutants, exhibit enamel hypoplasia, while humans with AI carry mutations in the human homologues of MSX2 or SP6 genes." (PMID 33192593, 2020). "It has been found that in the absence of SP6, the inner dental epithelium loses its characteristic ability to proliferate rapidly, resulting in severe enamel hypoplasia." (PMID 36613925, 2022).
gastric cancer (2 papers, 2020 to 2021). A primary or metastatic malignant neoplasm involving the stomach. "The results suggested that the expression of ELK3 and SP6 is increased in gastric cancer, and the expression of ZNF300 and MEF2B is down-regulated in gastric cancer." (PMID 34233659, 2021). "The functions of ZNF823, ZFP69B, SP6, KYNU, KIF21B, and TTF2 have not been reported in gastric cancer." (PMID 32848739, 2020).
lung fibrosis (2 papers, 2022 to 2025). "The SP6 gene is associated with Hermansky–Pudlak syndrome (HPS), which is associated with pulmonary fibrosis." (PMID 35052452, 2022). "Serum SP-6 and KL-6 may serve as suitable screening tools for detecting lung fibrosis during health checkups due to their high sensitivities and reasonable positivity rates." (PMID 41408239, 2025).
prostate carcinoma (2 papers, 2021 to 2024). A carcinoma that arises from epithelial cells of the prostate gland. "The SP6 gene was recently linked to an increased risk of prostate cancer, as well as to more aggressive disease." (PMID 39199676, 2024).
Alzheimer disease (1 paper, 2017). A progressive, neurodegenerative disease characterized by loss of function and death of nerve cells in several areas of the brain leading to loss of cognitive function such as memory and language. "SP6 is expressed in the hippocampus and amygdala and has been implicated in cognitive decline in Alzheimer's disease." (PMID 28480579, 2017). "Cg02219949 is located in the first intron of Sp6 transcription factor (SP6), a gene implicated in early development, cell proliferation, and previously associated with cognitive decline in Alzheimer Disease." (PMID 28480579, 2017).
Amelia (1 paper, 2014). Congenital absence (aplasia) of one or more limbs. "A progressive reduction in the dose of Sp6 and Sp8 gene products leads to predictable morphology, from syndactyly, to SHFM, oligodactyly, truncation and finally amelia." (PMID 25166858, 2014).
amyloid (1 paper, 2019). "We confirmed that ROCK1‐associated transcription factors, SP1 and SP6, were associated with amyloid production and up‐regulated in AD mouse model and those results were consistent with previous reports." (PMID 31287605, 2019).
asthma (1 paper, 2019). "For the region associated with SP6, the direction of change of DNA methylation was different; a reduction in DNA methylation in cells isolated from individuals with asthma in bronchial brush isolated cells versus an increase in DNA methylation in the combined dataset." (PMID 31595000, 2019).
bladder cancer (1 paper, 2025). "In contrast, EV samples derived from both GCB‐sensitive and GCB‐resistant bladder cancer cell lines, including SP3 (T24 EVs), SP4 (T24GCB EVs), SP5 (5637 EVs) and SP6 (5637GCB EVs), showed no detectable GCB signal." (PMID 41159684, 2025).
colitis (1 paper, 2022). Inflammation of the colon. "A colitis model was induced in rats with 2, 4, 6-trinitrohydrosulfonic acid (TNBS), followed by ST36 and SP6 targeted therapy by EA or sham EA treatment." (PMID 35087621, 2022).
Dysmenorrhea (1 paper, 2014). Pain during menstruation that interferes with daily activities. "Our previous study focused on the therapeutic effect specificity of SP6 and GB39 and nearby nonmeridian point also showed that the effects of SP6 and GB39 on dysmenorrhea were significantly better than that of nearby nonmeridian point." (PMID 24876879, 2014).
glioma (1 paper, 2021). A benign or malignant brain and spinal cord tumor that arises from glial cells (astrocytes, oligodendrocytes, ependymal cells). "Specific cytotoxic activity and CAR+ T cell expansion were further confirmed by co-culture of SP6 and p32 mCAR T cells with GFP+ glioma cells and analyzed by flow cytometry." (PMID 34127674, 2021).
Infertility (1 paper, 2022). "SP6 belongs to the spleen Meridian of Foot-Taiyin, which mainly treats gynecological and obstetric diseases such as irregular menstruation, dysmenorrhea, and infertility." (PMID 36578784, 2022).
insomnia (1 paper, 2021). A sleep disorder characterized by difficulty in falling asleep and/or remaining asleep. "SP6 was used to alleviate irregular menstruation and insomnia." (PMID 34122593, 2021).
iron-deficiency (1 paper, 2007). "From the current studies we conclude that SP6 is highly induced during iron-deficiency, thus making it a strong candidate for being involved in the genetic response to iron-deficiency." (PMID 18005439, 2007). "This prediction combined with the experimental observation that SP6/KLF14 is strongly induced by iron-deficiency suggests that SP6 could be involved in this genetic response." (PMID 18005439, 2007).
lymphoma (1 paper, 2021). A malignant (clonal) proliferation of B- lymphocytes or T- lymphocytes which involves the lymph nodes, bone marrow and/or extranodal sites. "However, expression of the exhaustion markers PD-1, LAG-3, and TIM-3 were not upregulated on CXCR5 CAR-T compared to SP6 CAR-T cells when we analyzed the persistence of CXCR5 CAR T cells in vivo at the time of lymphoma cell outgrowth." (PMID 33431832, 2021).
monocytopenia (1 paper, 2025). "While CAR T-cell expansion and splenomegaly were dependent on B7-H3-CAR expression, transient lympho- and monocytopenia also occurred post Reg-1 KO T cells that expressed a CAR specific for an irrelevant antigen (SP6)." (PMID 40475601, 2025).
morphine dependence (1 paper, 2014). Strong dependence, both physiological and emotional, upon morphine. "Based on these results, it is suggested that acupuncture stimulation of SP6 during protracted abstinence may inhibit the development of morphine dependence, and acupuncture therapy can be a powerful regulator of psychiatric disorders as well as a potential therapy against disease." (PMID 24527041, 2014).
myeloma (1 paper, 2022). "We observed strong myeloma progression localized to typical myeloma sites in bone marrow of miR-H18 SP6 CAR T cell-treated mice over 2 weeks, significantly less expansion in the BCMA CAR T cell cohort, and potent suppression of tumor growth in the miR-H18 BCMA CAR T cell group." (PMID 35821635, 2022).
neuroblastoma (1 paper, 2019). Neuroblastoma (NB) is the most common solid, extracranial childhood tumor. "Therefore, the antioxidant and neuroprotective capacities of SP6 against oxidative stress were assayed by using the human SH-SY5Y neuroblastoma cell line." (PMID 31216771, 2019).
Obesity (1 paper, 2020). Accumulation of substantial excess body fat. "Acupoint analysis revealed ST25, CV12, CV4, SP6, and ST36 to be most effective in the treatment of obesity with electroacupuncture." (PMID 32714399, 2020).
premenstrual syndrome (1 paper, 2023). "Imaging evidence supports that acupuncture stimulation associated with SP6 modulates neural activity in patients with premenstrual syndrome." (PMID 36897670, 2023).
psychosis (1 paper, 2017). "While AH volume ratio related to psychosis‐like symptoms in early adulthood, we found that at birth and age 7, methylation of a probe in the first intron of the gene SP6 predicted increased AH volume ratio after FDR correction." (PMID 28480579, 2017). "Using a cross‐sectional replication sample of patients with schizophrenia and healthy controls, we were able to further support the link between SP6 DNA methylation, AH volume ratio, and psychosis." (PMID 28480579, 2017).
psychosomatic disorders (1 paper, 2014). "SP6 has been used clinically to treat mental and psychosomatic disorders and is known to produce a sedative, tranquilizing, and antiemetic effect under a variety of stresses." (PMID 24527041, 2014).
schizophrenia (1 paper, 2017). A major psychotic disorder characterized by abnormalities in the perception or expression of reality. "The association between SP6 DNA methylation, AH volume ratio and psychopathology was replicated in an independent dataset of 101 patients with schizophrenia and 111 healthy controls." (PMID 28480579, 2017).
tumor (8 papers, 2012 to 2025). "The Ki-67 labeling index was assessed using immunohistochemical analysis with the monoclonal antibody clone SP6, representing the percentage of tumor cells showing positive staining." (PMID 39202532, 2024). "All the indicated tumor cell lines were co-cultured with control anti-TNP SP6 mCAR T26 or p32 mCAR T cells at different effector T cell to tumor cell (E:T) ratios." (PMID 34127674, 2021). "The exhaustion markers PD-1, LAG-3, and TIM-3 were not differentially upregulated over 13 days on BM or splenic localized CD4+ and CD8+ CXCR5 CAR-T compared to SP6 CAR-T cells, thus exhaustion seems to be unlikely involved in loss of tumor control." (PMID 33431832, 2021). "Tumor load in the BM was profoundly reduced in mice treated with CXCR5 CAR-T cells compared with SP6 CAR-T cells at day 8, and in BM and spleen at day 13 as well." (PMID 33431832, 2021). "The anti-tumor effects of SP6 were also confirmed in an HCT116 tumor xenograft model." (PMID 30214682, 2018). "We expected SP10 to have stronger anti-tumor effects compared to SP6." (PMID 30214682, 2018). "The SP0 (dsRed+) TDECs and SP6 (GFP+) TDECs were then mixed in equal numbers, combined with untagged H460 cells at a 1∶20 ratio as before, and grown as tumor xenografts." (PMID 22623986, 2012). "To gain mechanistic insight into the functional state of Reg-1 KO B7-H3-CAR, Ctrl KO B7-H3-CAR, or Reg-1 KO SP6-CAR T cells and their effects on endogenous immune cells, we euthanized F331 tumor-bearing mice on day 7 or day 21 or M119 tumor-bearing mice on day 7 or day 28 post CAR T cell infusion." (PMID 40475601, 2025). "At present, there is no experimental study on the mechanism of SP6 in affecting tumor progression." (PMID 34233659, 2021).
cancer (6 papers, 2018 to 2025). A tumor composed of atypical neoplastic, often pleomorphic cells that invade other tissues. "Given this evidence, further research is needed to investigate the role of AKR1B15, MTATP8P1, and SP6 in cancer." (PMID 38086955, 2023). "Our results show that EA ST36 and SP6 inhibited the most detrimental effects of cisplatin in normal and cancer mice." (PMID 34552585, 2021). "This also corresponds with improved cancer-related fatigue recovery through acupuncture at LI4, KI3, ST36, and SP6." (PMID 41390393, 2025). "To evaluate the anti-cancer effects of SP6 and SP10, we examined the cell viability of four cancer cell lines using the XTT cell viability assay." (PMID 30214682, 2018). "In this study, we focused on the usefulness and safety of SP6 and SP10 as anti-cancer drugs, and examined their anti-cancer effects and toxicity." (PMID 30214682, 2018). "The results showed that SP6 and SP10 inhibited cancer cell proliferation by inducing apoptosis in HCT116, HSC-2, A549, and MCF-7 cancer cells." (PMID 30214682, 2018). "There were fewer anti-proliferative effects of SP6 and SP10 in WI-38 and NIH-3T3 fibroblasts compared to the cancer cells." (PMID 30214682, 2018). "SP6 and SP10 suppressed the proliferation of cancer cells in a dose-dependent manner." (PMID 30214682, 2018). "Thus, in this study, we focused on the usefulness and safety of SP6 and SP10 as anti-cancer drugs, and examined their anti-cancer effects and toxicity." (PMID 30214682, 2018). "However, there is currently no research on the role of AKR1B15, MTATP8P1, and SP6 in cancer." (PMID 38086955, 2023).
infection (3 papers, 2022 to 2025). The state of being infected such as from the introduction of a foreign agent such as serum, vaccine, antigenic substance or organism. "While this bottleneck at early stages of S.Tm θ infection was predominantly sp22-mediated, at the highest CFU/g achieved by this strain (81,500 CFU/g), there was evidence of infection of macrophage (sp8 cells) as well as neutrophils (sp1, sp2, sp6)." (PMID 40462990, 2025). "Importantly, supplementation with SP6 TSP did not further enhance the EOP on the ΔwaaL deletion strain, demonstrating that it functions to remove the O-antigen barrier to FO1 infection." (PMID 41211961, 2025).
gynecological diseases (1 paper, 2019). "The occurrence of gynecological diseases is closely related to these three internal organs; SP6 is thus the key point for the treatment of gynecological diseases." (PMID 31341497, 2019).
neurodegenerative disease (1 paper, 2019). A disorder of the central nervous system characterized by gradual and progressive loss of neural tissue and neurologic function. "SP6 has great potential for developing novel pharmacological approach for neurodegenerative diseases, such as PD." (PMID 31216771, 2019).
neurological diseases (1 paper, 2014). "Activations in these regions may be consistent with its widespread functions of SP6 in mental, gynecological, and neurological diseases as recorded." (PMID 25024729, 2014).
peripheral neuropathy (1 paper, 2023). A disorder affecting the peripheral nervous system. "The distant SAPs of ‘KI3, LI4, and SP6’ are commonly used in managements of pain syndrome or peripheral neuropathy." (PMID 37539212, 2023).
SP6 also shares sentences with these, for which no sentence is quoted: Cognitive impairment (2 papers); cognitive decline (1); dementia (1); injury (1); kidney (1); leukemia (1); liver (1); ovarian carcinoma (1); peritonitis (1); Poland syndrome (1); psychiatric disorder (1); Splenomegaly (1); Stroke (1); viral infection (1).